ALKBH5 (alkB homolog 5, RNA demethylase)
Diseases named in the same sentence as ALKBH5 in open-access papers (continued):
Sharing a sentence is not in itself a finding about the gene and the disease.
Autoimmunity (5 papers, 2022 to 2024). The occurrence of an immune reaction against the organism's own cells or tissues. "ALKBH5 controls the pathological effects of CD4+ T cells during autoimmunity." (PMID 35682869, 2022). "As IFN-γ is an important anti-tumor cytokine and ALKBH5 has a positive effect on the expression of IFN-γ in autoimmunity, ALKBH5 may have the potential to positively regulate the anti-tumor effect of CD4+ T cells." (PMID 35296338, 2022). "ALKBH5 modulated CD4+ T cells to respond and enhance autoimmunity." (PMID 39229575, 2024).
brain tumor (5 papers, 2020 to 2025). "This study demonstrates that USP14 plays a role in the RNA m6A pathway and brain tumor biology by stabilizing ALKBH5." (PMID 39990235, 2025). "In brain tumors, the two m6A mRNA demethylases FTO and ALKBH5 have been clearly associated to pro-oncogenic functions, promoting cell proliferation, self-renewal, and the progression of GBMSC-initiated tumors." (PMID 33375621, 2020). "Furthermore, knockdown of ALKBH5 impaired the tumorigenicity of GSC cells because the brain tumor formation rate of the GSCs with ALKBH5 knockdown was smaller as compared with control cells." (PMID 38398118, 2024). "Inhibiting USP14 with the small molecule IU1 disrupts ALKBH5 deubiquitylation and increases the effectiveness of IR therapy on GSC-derived brain tumor xenografts." (PMID 39990235, 2025). "Again, there are several conflicting reports of m6A regulator expression levels among the different brain tumour entities and non-tumour brain tissue, including ALKBH5, WTAP, METTL14, and YTHDC2." (PMID 36831575, 2023).
mental disorder (5 papers, 2017 to 2026). A disease that has its basis in the disruption of mental process. "In our present study, four m6A feature regulators (YTHDC1, IGFBP1, IGF2BP1, and ALKBH5), critically implicated in psychiatric disorders and neurodegenerative diseases, were identified to be associated with PTSD." (PMID 41149057, 2025). "Recently, an SNP in the ALKBH5 gene was identified in association with major mental disorders in the Chinese Han population." (PMID 28931651, 2017). "In summary, these studies unveil the important regulatory role of ALKBH5 in neurodevelopment and neurodegenerative and mental illness." (PMID 40001461, 2025).
Miscarriage (5 papers, 2020 to 2025). A pregnancy that ends at a stage in which the fetus is incapable of surviving on its own, defined as the spontaneous loss of a fetus before the 22th week of pregnancy. "This indicates that the main mechanism of action of hsa_circ_0069443 in miscarriage is through the regulation of ALKBH5 protein expression." (PMID 39868042, 2025). "ALKBH5 expression was found to increase in trophoblasts under hypoxia but decrease in EVT of patients with recurrent spontaneous abortion (RSA)." (PMID 39192357, 2024). "This study explored whether the role of hsa_circ_0069443 in miscarriage depends on its regulatory effect on ALKBH5." (PMID 39868042, 2025). "In addition to its influence on reproductive system cancer progression and germ cell development, ALKBH5 has been reported to impact female miscarriage as well." (PMID 40001461, 2025). "Additionally, studies on recurrent miscarriage (RM) patients revealed a significant decrease in placental villous tissue mRNA m6A methylation levels without specific ALKBH5 expression regulation." (PMID 39192357, 2024).
oral squamous cell carcinoma (5 papers, 2020 to 2024). "Later, another study confirmed that ALKBH5 is directly regulated by DDX3 in oral squamous cell carcinoma cells." (PMID 35063010, 2022). "Furthermore, we performed IHC staining for YTHDC2 and ALKBH5 proteins in 20 pairs of normal and oral squamous cell carcinoma tissues to confirm such findings." (PMID 32547941, 2020). "However, the roles of RNA m6A demethylases, fat mass and obesity-associated protein (FTO), and AlkB homolog 5 (ALKBH5) in oral epithelial dysplasia (OED) and oral squamous cell carcinoma (OSCC) remain unclear." (PMID 36582218, 2023).
uveal melanoma (5 papers, 2021 to 2024). A melanoma derived from melanocytes of the uveal tract. "For instance, METTL3, an m6A ‘writer’, was downregulated in ocular melanoma tissues, and m6A demethylation of FOXM1 mRNA mediated by ALKBH5 was associated with uveal melanoma (UM) progression." (PMID 36264762, 2022). "Hao and colleagues reported that ALKBH5‐mediated m6A demethylation of FOXM1 mRNA promotes malignancies of uveal melanoma, which demonstrated that ALKBH5 increased FOXM1 stability by demethylating FOXM1 mRNA." (PMID 38098223, 2024). "In this study, we found that ALKBH5, a key component of the N6-methyladenosine (m6A) methyltransferase complex, was significantly elevated in uveal melanoma (UM) cell lines and that ALKBH5 downregulation inhibited tumor growth in vivo." (PMID 33428593, 2021). "Hao and colleagues found that, ALKBH5 mediates m6A demethylation of FOXM1 mRNA and promotes progression of uveal melanoma." (PMID 38098223, 2024). "Epigenetic dynamics of ALKBH5 has also been researched in HBV-HCC, uveal melanoma (UM) and NSCLC." (PMID 35063010, 2022).
Anxiety (4 papers, 2020 to 2025). Intense feelings of nervousness, tension, or panic often arise in response to interpersonal stresses. "When ALKBH5 was deleted specifically in mPFC astrocytes, antidepressant-like behavior was still observed, but the anxiety levels of the knockout mice remained unchanged in both the EPM and LDB tests." (PMID 40141416, 2025). "However, some concerns remain regarding the role that astrocyte ALKBH5 plays in anxiety behavior, as the deletion of ALKBH5 in neurons of the olfactory bulb similarly resulted in an increased anxiety state." (PMID 40141416, 2025). "Under AAV‐mediated overexpression of Alkbh5, mice presented with lower levels of total m6A in the PFC, even with the exercise intervention and displayed anxiety‐like behaviors." (PMID 35642952, 2022).
Arthritis (4 papers, 2020 to 2025). Inflammation of a joint. "Some researchers also had found that the expression of ALKBH5 was increased in RA synovial tissues, collagen-induced arthritis model rats, and RA fibroblast-like synoviocytes (FLSs), and a hypoxic environment increased the expression of ALKBH5 in FLSs." (PMID 41479914, 2025). "Subsequently, we evaluated the relationship between the clinical symptoms of SLE including LN, NPLE, arthritis, fever, rash, alopecia, ulceration, pleuritis, pericarditis, and the expression of METTL14, ALKBH5, and YTHDF2 in PBMCs." (PMID 32583611, 2020). "The severity of arthritis was also found to be reduced in ALKBH5 knockout delayed-type hypersensitivity arthritis (DTHA) model mice or collagen-induced arthritis (CIA) and rats injected intra-articularly with ALKBH5-shRNA RNA." (PMID 39072324, 2024).
breast tumor (4 papers, 2020 to 2025). "Interestingly, a report showed that ALKBH5 is directly methylated at the R283 site by the ADMA modification of PRMT6, which thus promotes the formation of breast tumors." (PMID 39781264, 2025).
endometriosis (4 papers, 2021 to 2025). The growth of functional endometrial tissue in anatomic sites outside the uterine body. "Endometriosis patients with a high expression of CBLL1 and METTL3 showed a notably high expression level of ALKBH5." (PMID 36672827, 2022).
fibrosis (4 papers, 2023 to 2026). the formation of excess fibrous connective tissue in an organ or tissue in a reparative or reactive process. "ALKBH5 is implicated in macrophage-to-myofibroblast transition (MMT), and the accompanying cardiac fibrosis and dysfunction caused by hypertension." (PMID 41007655, 2025). "Our data showed that Alkbh5 deficiency protected against I/R-induced AKI and fibrosis." (PMID 36859428, 2023). "In our findings, the suppression of ALKBH5 promoted the expression of COL3A1, COL1A1 and ELN, and these increased ECM components were subsequently secreted and deposited within the dermis, culminating in dermal fibrosis and scar hyperplasia." (PMID 39233335, 2024).
Hypertension (4 papers, 2024 to 2025). The presence of chronic increased pressure in the systemic arterial system. "Specific deletion of ALKBH5 in macrophage inhibits hypertension or pressure overload induced MMT, and subsequently attenuates pathological cardiac fibrosis and diastolic dysfunction, via regulating m6A modification on IL-11 mRNA." (PMID 38443404, 2024). "Under AngII-induced hypertension, ALKBH5 mediated the m6A demethylation of IL-11 mRNA, leading to increased stability and protein level of IL-11, promoting AngII-induced MMT, resulting in cardiac fibrosis and functional impairment." (PMID 39220683, 2024). "Under AngII-induced hypertension, ALKBH5 mediated m6A demethylation of IL-11 mRNA to increase the stability IL-11, promoting AngII-induced MMT, and resulted in cardiac fibrosis." (PMID 39220683, 2024). "We therefore hypothesized that ALKBH5 might contribute to hypertension-induced MMT, and related cardiac fibrosis and dysfunction." (PMID 38443404, 2024). "To investigate the mechanism by which ALKBH5 regulates MMT and cardiac fibrosis under hypertension, we performed ALKBH5 RNA immunoprecipitation-sequencing (RIP-seq) in cultured macrophages and found several genes are the direct targets of ALKBH5." (PMID 38443404, 2024).
ischemia (4 papers, 2021 to 2025). A hypoperfusion of the BLOOD through an organ or tissue caused by a PATHOLOGIC CONSTRICTION or obstruction of its BLOOD VESSELS, or an absence of BLOOD CIRCULATION. "Next, the ex vivo model of vessel sprouting and the in vivo hind‐limb ischemia were used to verify the angiogenic regulatory role of ALKBH5." (PMID 34047466, 2021). "Mice with ALKBH5 overexpression exhibited significantly decreased blood flow recovery rates on days 7–21 after hind‐limb ischemia compared with control mice." (PMID 34047466, 2021). "Here, we reported that the silencing of ALKBH5 results in impaired endothelial tube formation following ischemia." (PMID 35127873, 2021). "ALKBH5 increased in the early stages of ischemia (within 6 h) compared with the non‐ischemia group." (PMID 34047466, 2021). "It is worth noting that the impact of ALKBH5 KO on angiogenesis was tested in hind‐limb ischemia." (PMID 34047466, 2021). "Further, we demonstrated that ALKBH5 maintains SPHK1 protein level and eNOS phosphorylation (which is required to regulate EC tube formation) following ischemia in ECs." (PMID 35127873, 2021).
malignant glioma (4 papers, 2019 to 2022). A grade III or grade IV glioma arising from the central nervous system. "ALKBH5 is able to maintain stem cell in malignant glioma cells, and ALKBH5-mediated m6A modification on forkhead box M1 (FOXM1) mRNA is involved in the maintenance of tumor stem cell." (PMID 31452869, 2019). "In addition, some studies also indicated that ALKBH5 overexpression triggered the development and invasion of malignant glioma by increasing FOXM1 expression products." (PMID 35004726, 2021).
pancreatic adenocarcinoma (4 papers, 2021 to 2022). "First, we performed gene expression correlation analysis using 178 pancreatic adenocarcinoma (PAAD) samples according to the Cancer Genome Atlas (TCGA) database to explore their correlation with ALKBH5." (PMID 34733841, 2021). "For instance, both arm-level gain and deletion of ALKBH5 is relation to decreased infiltration of CD8 + T cell in pancreatic adenocarcinoma." (PMID 34603372, 2021).
renal fibrosis (4 papers, 2020 to 2025). A final common manifestation of a wide variety of chronic kidney diseases characterized by glomerulosclerosis and tubulointerstitial fibrosis. "However, genistein pretreatment restored ALKBH5 loss remarkably and reduced renal fibrosis, abnormal protein, and inflammatory markers." (PMID 33364952, 2020). "Recently, several studies have also explored the role of ALKBH5 in organ fibrotic diseases such as pulmonary and renal fibrosis." (PMID 39233335, 2024). "In conclusion, genistein increased renal ALKBH5 expression in UUO-induced renal fibrosis and reduced RNA m6A levels and ameliorates renal damages." (PMID 33364952, 2020). "ALKBH5 is a crucial regulator for the m6A modification and protection of genistein for renal fibrosis." (PMID 33364952, 2020). "As an eraser, ALKBH5 showed severer suppression in the renal fibrosis process." (PMID 33364952, 2020). "We verify whether the anti-renal fibrosis impact of genistein was in relation to ALKBH5 restoration." (PMID 33364952, 2020). "Genistein ameliorates renal fibrosis by restoring ALKBH5 to regulate EMT." (PMID 33364952, 2020). "Thus, we believe that ALKBH5 is a crucial regulatory gene involved in how genistein protects renal fibrosis." (PMID 33364952, 2020). "Therefore, the effect of ALKBH5 on renal fibrosis needed further study." (PMID 39220683, 2024). "This also suggested that inhibiting ALKBH5 could slow down the progression of renal fibrosis." (PMID 39220683, 2024). "In this study, we first examined whether and how ALKBH5 modulates renal fibrosis." (PMID 33364952, 2020). "m6A RNA methylation was found to be significantly elevated in renal fibrosis, accompanied by increased expression of key m6A regulators, including METTL3, METTL14, ALKBH5, YTHDF1, and YTHDF3." (PMID 39756462, 2025). "In the I/R-induced renal injury model of male mice, researchers found that knocking down ALKBH5 increased the expression of CCL28 through m6A modification, regulated the downstream CCL28/Treg/inflammatory cell axis, thereby alleviating I/R-induced acute kidney injury and renal fibrosis." (PMID 39220683, 2024). "In a mouse model of renal fibrosis induced by UUO, overexpression of ALKBH5 could increase the expression of the renal epithelial adhesion molecule E-cadherin while decreasing the expression of snail, thereby alleviating UUO-induced renal fibrosis by affecting the EMT process." (PMID 39220683, 2024).
asthma (3 papers, 2022 to 2024). "m6A methylation plays an essential role of in the pathogenesis of asthma; mRNA and protein levels of METTL14 and ALKBH5 are significantly decreased in asthma." (PMID 39011034, 2024). "The results showed that the expression of known m6A writers (i.e., METTL3 and METTL14), erasers (i.e., FTO and ALKBH5), and readers (i.e., YTHDF3) was moderately downregulated in peripheral blood mononuclear cells (PBMCs) of human asthma sufferers." (PMID 37957139, 2023). "In the asthma group, the mRNA and the protein level of METTL14 (the key methyltransferase) and ALKBH5 (the major demethyltransferase) were significantly decreased compared with the control group (P<0.01)." (PMID 36250525, 2022). "Moreover, the precise functions of METTL14, ALKBH5, and m6A methylation of IL17RB mRNA and lncRNAs in asthma need to be further elucidated." (PMID 36250525, 2022).
autoimmune disease (3 papers, 2022 to 2025). A disorder resulting from loss of function or tissue destruction of an organ or multiple organs, arising from humoral or cellular immune responses of the individual to their own tissue constituents. "The reduced expression of FTO, and ALKBH5 in JIA monocytes mirrors observations in other autoimmune disorders." (PMID 41009809, 2025). "Moreover, many reports have explored the relevance between YTHDF2, ALKBH5, and clinical features of autoimmune disease." (PMID 35755020, 2022). "Thus, XFC exerts therapeutic effects via the ALKBH5/LINC00968/m6A pathway, providing a compelling example of TCM targeting epitranscriptomic mechanisms in autoimmune diseases." (PMID 41479914, 2025).
B cell lymphoma (3 papers, 2022 to 2025). "In addition, ALKBH5 is related to the growth of Myc-dysregulated B-cell lymphoma, and inhibition of ALKBH5 can effectively inhibit the growth of MYC-dysregulated B-cell lymphoma, both in vitro and in vivo." (PMID 36902149, 2023).
cholangiocarcinoma (3 papers, 2020 to 2024). A carcinoma that arises from the intrahepatic biliary tree (intrahepatic cholangiocarcinoma) or from the junction, or adjacent to the junction, of the right and left hepatic ducts (hilar cholangiocarcinoma). "ALKBH5 has been reported to maintain PD-L1 expression through the ALKBH5-PD-L1 regulatory axis in intrahepatic cholangiocarcinoma while inhibiting T-cell growth and infiltration." (PMID 39033180, 2024). "For example, only ALKBH5 was relevant to the cholangiocarcinoma survival, which illustrates heterogeneity of the m6A system in tumors." (PMID 33273988, 2020).
female infertility (3 papers, 2023 to 2025). Diminished or absent ability of a female to achieve conception. "Meanwhile, oocytes with ALKBH5 deficiency exhibited impaired RNA clearance and meiosis disruption, which affected ovarian function and caused female infertility." (PMID 40001461, 2025). "Here, we show that Alkbh5 depletion causes a wide range of defects in oocyte meiosis and results in female infertility." (PMID 37848452, 2023). "For example, the upregulation of m6A mediated by ALKBH5 deletion hindered the timely attenuation of RNA during oocyte meiosis, which resulted in widespread defects in oocytes and led to female infertility." (PMID 40001461, 2025).
gastric adenocarcinoma (3 papers, 2021 to 2024). "Another m6A reader, ALKBH5, and its associated genes significantly influence the immune microenvironment in GC, particularly in stomach adenocarcinoma (STAD), although the findings are at times contradictory and ambiguous." (PMID 39199429, 2024).
Hepatic steatosis (3 papers, 2024 to 2025). Steatosis is a term used to denote lipid accumulation within hepatocytes. "In a mouse model of NAFLD, inhibiting ALKBH5 regulated hepatic autophagy flux, thereby alleviating hepatic steatosis and fibrosis." (PMID 39220683, 2024). "Decreased ALKBH5 causes increased m6A modification and increased expression of ATG12 in a demethylase activity-dependent manner, thereby promoting autophagy and preventing hepatic steatosis." (PMID 40428320, 2025). "Chlorogenic acid (CGA), a naturally occurring plant component, could inhibit ALKBH5 activity to regulate autophagy and alleviate hepatic steatosis." (PMID 39220683, 2024). "By blocking the activity of the RNA demethylase AlkB homolog 5 (ALKBH5), studies have also demonstrated that CGA can control autophagy and reduce hepatic steatosis." (PMID 41142236, 2025).
ischemic disease (3 papers, 2020 to 2025). Lack of blood supply to an area of the body, resulting in impairment of tissue oxygenation. "Targeting ALKBH5 may be a potential therapeutic option for ischemic diseases, including peripheral artery disease." (PMID 34047466, 2021). "In terms of potential translational implications, our experiments reveal that blocking ALKBH5 might be a therapeutic alternative for ischemic diseases." (PMID 34047466, 2021). "Our findings also indicate that ALKBH5 /m6A axis influences the blood flow recovery and post‐ischemic angiogenesis in hind‐limb ischemia mice, and targeting ALKBH5 might be a potential option to treat ischemic diseases, including PAD." (PMID 34047466, 2021). "Present results illustrate that ALKBH5 is a key m6A demethylase involved in regulating angiogenesis and post‐ischemic insult, thus providing experimental data for the potential therapeutic role of targeting ALKBH5 in the management of ischemic diseases via promoting post‐ischemic angiogenesis." (PMID 34047466, 2021). "In addition, transcription factor EB activates the transcription of ALKBH5 and downregulates the stability of METTL3 mRNA in hypoxia/reoxygenation-induced autophagy in ischemic diseases." (PMID 31931709, 2020).
ischemic stroke (3 papers, 2022 to 2024). A stroke disorder caused by obstruction of blood flow to the brain, due to thrombotic (local blood clot formation) or embolic (due to a blood clot or other material traveling from another site) event. "Additionally, ALKBH5 protects against ischemic stroke by reducing neuronal apoptosis." (PMID 39519091, 2024).